TGFBI (transforming growth factor beta induced)
Diseases named in the same sentence as TGFBI in open-access papers (continued):
Sharing a sentence is not in itself a finding about the gene and the disease.
keratoconus (4 papers, 2010 to 2021). A degenerative, structural disorder of the eye, characterized by a cone-shaped protrusion of the cornea. "Variants of VSX1 and TGFBI genes identified in both the clinically diagnosed and subclinical patients may cause the keratoconus through an autosomal dominant inheritance pattern, with different variable expressivity." (PMID 34136477, 2021). "The TGFBI variant was confirmed by Sanger DNA sequence analysis in the siblings, II.3 and II.5, who had hypocalcemia and keratoconus, but its absence in the sister II.4, who has hypocalcemia only, indicates that this TGFBI variant is not involved in the etiology of hypocalcemia." (PMID 26818911, 2016). "Keratoconus in this family was likely due to a novel germline TGFBI His403Gln variant, thereby indicating that keratoconus and ADH2 are not caused by the same mutation, but instead the combined occurrence of ADH2 and keratoconus in some family members is due to digenic inheritance." (PMID 26818911, 2016). "A novel His403Gln variant in transforming growth factor, beta‐induced (TGFBI), that may be causing keratoconus was also identified, indicating likely digenic inheritance of keratoconus and ADH2 in this family." (PMID 26818911, 2016). "In fact, VSX1 may have a pleiotropic action among the tissues of the cornea leading to keratoconus in some cases as observed for the transforming growth factor (TGFBI) gene; which causes four distinct autosomal dominant corneal diseases." (PMID 21139977, 2010).
liver disease (4 papers, 2019 to 2023). "Remarkably, in this unbiased analysis, four clinical markers used in liver disease—ALT, AST, ALP, and GGT—clustered into a single group together with a panel of five proteins of special interest—PIGR, DPP4, ANPEP, TGFBI, and APOE." (PMID 30824564, 2019). "The other four are also highly relevant for liver disease: APOE (apolipoprotein E), dipeptidyl peptidase‐4 (DPP4), TGFBI (transforming growth factor‐beta‐induced protein ig‐h3), and aminopeptidase N (ANPEP)." (PMID 30824564, 2019). "In addition, many novel liver disease biomarkers were discovered, such as EGF-containing fibulin-like extracellular matrix protein 1 (EFEMP1), SAA2, CPN2, ANPEP, TGFBI, and FGG." (PMID 37209815, 2023). "A very high correlation of TGFBi to overall fibrotic burden was observed in the liver, indicating that loss of Stab1 or Stab2 alone does not seem to impede scavenging of POSTN or TGFBi, even in liver disease models in these mice." (PMID 37446152, 2023).
myocardial infarction (4 papers, 2017 to 2025). Gross necrosis of the myocardium, as a result of interruption of the blood supply to the area, as in coronary thrombosis. "In acute myocardial infarction, activated platelets release transforming growth factor B-inducible (TGFBI) protein, which stimulates platelet activation, adhesion, migration, and vascular inflammation, thereby contributing to the disease progression of myocardial infarction (MI)." (PMID 40529502, 2025). "Thus, TGFBI and periostin act similarly in the heart in affecting fibrosis and disease responsiveness, although TGFBI is not seemingly necessary in the heart after myocardial infarction injury and is fully compensated by the more prominently expressed effector periostin." (PMID 28750100, 2017).
nasopharyngeal carcinoma (4 papers, 2018 to 2021). A carcinoma arising from the nasopharyngeal epithelium. "The overexpression of TGFBI sensitized the nasopharyngeal carcinoma (NPC) cells to cisplatin." (PMID 33912443, 2021).
oral squamous cell carcinoma (4 papers, 2019 to 2022). "With regard to oral squamous cell carcinoma, TGFBI was reported to potentially alter cell response to bacterial stress, leading to an imbalance of the inflammatory environment, promoting cancer development." (PMID 36157879, 2022). "Knockout of TGFBI inhibits the proliferation and metastasis of oral squamous cell carcinoma in vivo." (PMID 34217310, 2021). "Another study showed that the proliferation and metastasis ability of oral squamous cell carcinoma cells was also enhanced by TGFBI upregulation." (PMID 34671645, 2021).
type 1 diabetes (4 papers, 2022 to 2024). "Notably, human genome-wide association study (GWAS) data have shown that single-nucleotide polymorphisms in the vicinity of the TGFBI gene are associated with type 1 diabetes risk, and TGFBI has been shown to promote islet survival, function and regeneration in mice." (PMID 37537394, 2023). "In agreement with the observations from the cross-sectional serum proteomics study of Zhi and co-workers, TGF-β-induced protein ig-h3 (TGFBI) was less abundant in the individuals with type 1 diabetes." (PMID 37537394, 2023).
amyloid (3 papers, 2008 to 2025). "Corneal amyloid caused by the A546D mutation in TGFBI involves several proteins associated with other varieties of amyloidosis." (PMID 23592924, 2013). "In those corneal amyloidoses caused by mutations in TGFBI, it is clear that amyloid relates to mutations in specific codons." (PMID 18385782, 2008). "The Y571-R588 peptide of TGFBIp has also been found to specifically accumulate in the corneal amyloid in the LCD type 1 variant due to the V624M mutation in TGFBI, thus supporting the idea that this region is responsible for amyloidosis in LCDs linked to mutations in the FAS1–4 domain of TGFBIp." (PMID 23592924, 2013). "In the SMC-calc vs. SMC comparison based on limma, clusters related to high-density lipoprotein (HDL) assembly (PF4V1, APOA1, LPXN, AFP, A2M, and MMP1) and amyloidosis (CX3CL1, APOE, PLIN3, TGFBI, and CH25H) were identified." (PMID 41301179, 2025).
brain cancer (3 papers, 2010 to 2021). A primary or metastatic malignant neoplasm affecting the brain. "The expression association between TGFBI and miR-21 was shown to be significant with a P value of lower than 0.05 either in the NCI-60 cells or in 6 brain cancer cell lines (including SF-268, SF-295, SF-539, SNB-19, SNB-75 and U251 cell lines)." (PMID 27166186, 2016). "Two similar protein families, namely the fasciclin domain containing protein TGFBI (βig-H3), and chitinase-like proteins, CHI3L1 and CHI3L2, are present in mammals, and recent Massively Parallel Signature Sequencing (MPSS) analysis show similar expression pattern in brain cancer cells." (PMID 21124849, 2010).
esophageal cancer (3 papers, 2014 to 2021). A primary or metastatic malignant neoplasm involving the esophagus. "The TGFBI gene which is mapped to chromosome 5q31 is known to be deleted in several human cancers including renal, lung, esophageal cancers and leukemias." (PMID 25369402, 2014).
fibrosis (3 papers, 2024 to 2025). the formation of excess fibrous connective tissue in an organ or tissue in a reparative or reactive process. "Incorporating genotype information further improved the accuracy of classifying patients with fibrosis stages F0–F1 versus F2–F4 using TGFBI." (PMID 39972214, 2025). "Levels of TGFBI in the liver correlate with the intensity of perisinusoidal fibrosis in Stab1 KO." (PMID 38275881, 2024).
head and neck cancer (3 papers, 2020 to 2021). A primary or metastatic malignant neoplasm affecting the head and neck. "In thirty-three TCGA transcriptomic cohorts, TGFBI was a poor indicator of seven cancer types, including head and neck cancer; HYAL1 was a protective marker for four cancer types, including kidney renal clear cell carcinoma and uveal melanoma." (PMID 34869001, 2021). "In The Cancer Genome Atlas, TGFBI was a poor marker not only for head and neck cancer but also for additional six cancer types and HYAL1 was a good indicator for four tumor cohorts, suggesting common stromal effects existing in different cancer types." (PMID 34869001, 2021). "In 33 TCGA datasets, TGFBI was recapitulated as a poor indicator for seven cancer types, including head and neck cancer comprising 519 patients." (PMID 34869001, 2021). "It was reported that TGFBI expressed higher in tumors than adjacent normal specimens within head and neck cancer patients." (PMID 33489877, 2020).
kidney cancer (3 papers, 2021 to 2024). Primary or metastatic malignant neoplasm involving the kidney. "Additionally, different levels of protein expression intensity of TGFBI were observed in kidney cancer tissues but not detected in normal tissues." (PMID 36035369, 2022).
lung squamous cell carcinoma (3 papers, 2018 to 2021). "High TGFBI level was associated with longer survival in lung squamous cell carcinomas patients received adjuvant platinum-based chemotherapy." (PMID 33912443, 2021). "The results are consistent with a previous study reporting that TGFBI is a favorable prognostic factor for survival in patients with squamous cell lung cancer treated with adjuvant platinum-based chemotherapy." (PMID 29795279, 2018).
lymph node metastasis (3 papers, 2017 to 2024). "Besides, high expression of SPRY1 suggested low risk of lymph node metastasis, whereas the high expression of TGFBI suggested high risk of lymph node metastasis." (PMID 36035369, 2022). "High expression levels of TGFBI in the cytoplasm were related to lymph node metastasis and distant metastasis." (PMID 28229027, 2017). "Notably, high TGFBI expression exhibited a higher incidence of lymph node metastasis compared with low TGFBI expression." (PMID 38514830, 2024).
mesenchymal tumors (3 papers, 2002 to 2023). "The combination of the expression of the genes PLAU, LAMB1, COL6A1, and TGFBI classified correctly the majority of mesenchymal tumors." (PMID 38031074, 2023). "More recently, down-regulation of TGFBI expression has been reported to be involved in the development of human tumors, including lung, breast, ovarian, prostate, embryonic rhabdomyosarcoma, insulinoma, and mesenchymal tumors." (PMID 22695319, 2012).
Obesity (3 papers, 2022 to 2024). Accumulation of substantial excess body fat. "Our findings revealed a novel protective effect of TGFBI deficiency in obesity that is realized via the activation of the Notch-1 signaling pathway." (PMID 36854775, 2023). "Our findings establish the importance of TGFBI in regulating adipose metabolism in obesity and present the mechanisms underlying this effect." (PMID 36854775, 2023). "Similarly, AdEVs-proteins (RBP4, perilipin-A, FABP, mimecan, TGFBI) and AdEVs-lipids (sphingolipids) have been linked to the obesity pathophysiology." (PMID 38988671, 2024). "Taken together, our findings offer new insights for the development of new therapeutic approaches for obesity and related disorders via TGFBI regulation." (PMID 36854775, 2023). "In the present study, we demonstrated that the ECM component TGFBI plays a role in HFD-induced obesity and improves several physiological conditions, such as glucose/insulin resistance, adipose expansion, liver steatosis, and adipocyte differentiation." (PMID 36854775, 2023). "Taken together, these results suggest that TGFBI KO mice had an improved capacity for obesity-induced metabolic changes." (PMID 36854775, 2023). "To explore the mechanisms underlying the protective effects of TGFBI during obesity, we examined the PPARγ signaling pathway, which is closely involved in adipocyte differentiation, in iWAT from ND- and HFD-fed WT and TGFBI KO mice." (PMID 36854775, 2023). "We found that TGFBI KO mice were protected against obesity, as shown by the limited adipose expansion and improved insulin/glucose homeostasis." (PMID 36854775, 2023). "Therefore, we suggest that TGFBI contributes to specific adipose tissue and adipocyte characteristics, ultimately affecting whole-body metabolism and obesity." (PMID 36854775, 2023). "Studying a protein called TGFBI, which regulates adipose expansion, may help the development of new approaches to protect against obesity and related metabolic disorders such as type II diabetes." (PMID 36854775, 2023). "A genetically modified animal model was used to determine whether TGFBI affected diet-induced obesity." (PMID 36854775, 2023). "Based on the contribution of TGFBI to adipose angiogenesis, we investigated whether TGFBI functions as a regulator of chronic processes, such as adipose expansion and inflammation, and whether it can control metabolic health during obesity." (PMID 36854775, 2023). "In this study, we demonstrated that transforming growth factor-beta (TGFBI), an extracellular matrix (ECM) component, plays an important role in adipose metabolism and browning during high-fat diet-induced obesity." (PMID 36854775, 2023). "In the present study, we determined the role of TGFBI in adipose tissue expansion and related metabolic disorders using a mouse model of high-fat diet (HFD)-induced obesity." (PMID 36854775, 2023).
pancreatic ductal adenocarcinoma (3 papers, 2017 to 2025). An infiltrating adenocarcinoma that arises from the epithelial cells of the pancreas. "The extracellular matrix (ECM) protein Beta-Ig H3 (βigH3, also known as transforming growth factor β induced protein (TGFBI)) is related to poor prognosis in patients with pancreatic ductal adenocarcinoma (PDAC)." (PMID 40394523, 2025). "In addition, TGFBI activates the focal adhesion kinase signaling pathway by binding to integrin αVβ5, significantly enhancing the invasion of pancreatic ductal adenocarcinoma." (PMID 34671645, 2021). "Serum TGFBI concentration is therefore considered a potential biomarker in some gastrointestinal cancers; indeed, a proteomic analysis showed that TGFBI expression was higher in pancreatic ductal adenocarcinoma than in non-cancerous tissues." (PMID 28106769, 2017).
prostate adenocarcinoma (3 papers, 2008 to 2021). "MSP conditions were optimized and successfully used for examining the methylation status of the TGFBI promoter in 50 cases each of lung tumors and prostatectomy specimens of prostate adenocarcinoma patients." (PMID 18834524, 2008). "A PanCancer Atlas cohort of 494 prostate adenocarcinoma patients revealed a positive correlation between MIR100HG and TGFB1 expression, and even stronger correlation between MIR100HG and TGFBI expression." (PMID 33941855, 2021).
renal carcinoma (3 papers, 2019 to 2024). A carcinoma arising from the epithelium of the renal parenchyma or the renal pelvis. "In our study, knockdown of TGFBI inhibited the proliferation, migration and invasion of renal cancer cells." (PMID 39068456, 2024). "The knockdown efficiency was verified by Western blot and qRT-PCR, respectively, and the expression of TGFBI in renal cancer cells after transfection with siRNA was significantly decreased compared with that in normal renal tubular epithelial cells." (PMID 39068456, 2024). "In addition, it was also found for the first time that TGFBI may affect the proliferation and progression of renal cancer cells by influencing the tumor immune microenvironment." (PMID 39068456, 2024).
renal fibrosis (3 papers, 2015 to 2023). A final common manifestation of a wide variety of chronic kidney diseases characterized by glomerulosclerosis and tubulointerstitial fibrosis. "TGFBI has been shown to be induced by TGF-β and can affect heart and renal fibrosis." (PMID 36674597, 2023).
urothelial carcinoma (3 papers, 2019 to 2023). A malignant neoplasm derived from the transitional epithelium of the urinary tract (urinary bladder, ureter, urethra, or renal pelvis). "Here, we discovered TGFBI as a new urinary biomarker for muscle invasive and high-grade urothelial carcinoma (UC)." (PMID 31514337, 2019). "TGFBI companion diagnostics may be particularly valuable in such cases where histological sections cannot be completely evaluated (e.g., due to squeezing or cauterizing artefacts), or in terms of a verification analyses for a low-grade urothelial carcinoma." (PMID 31514337, 2019).
viral infection (3 papers, 2015 to 2022). "Among the 6 genes, over-expressed genes (HK3, DEFA4, BATF) were positively correlated with severity of viral infection, and under-expressed genes (HLA-DPB1, LY86, TGFBI) were negatively correlated with severity." (PMID 35042868, 2022). "Each of the 6 genes were significantly differentially expressed between patients with viral infections who survived and those who did not, of which 3 genes (DEFA4, BATF, HK3) were higher and 3 genes (TGFBI, LY86, HLA-DPB1) were lower in those who died." (PMID 35042868, 2022).
Allergy (2 papers, 2021 to 2024). An allergy is an immune response or reaction to substances that are usually not harmful. "The highest enriched pathway, positive regulation of IL-4 production, along with TGFBI (transforming growth factor beta induced), suggest that the V stimulus promoted immune-suppressive activity, which in mammals is associated with Th9 cells linked to allergy in asthma and autoimmunity." (PMID 39015564, 2024).
Autoimmunity (2 papers, 2019 to 2024). The occurrence of an immune reaction against the organism's own cells or tissues. "Interestingly, transforming growth factor, beta-induced (TGFBI) prevents autoimmunity by promoting T cell activation through Ca2+-calcineurin signaling." (PMID 31798633, 2019).
breast invasive carcinoma (2 papers, 2021 to 2023). "Subsequently, we investigated the correlation between CCL8, TGFBI expression levels and immune infiltrates in invasive breast cancer samples from the TCGA database, respectively." (PMID 37884960, 2023).
cervical squamous cell carcinoma (2 papers, 2021). A squamous cell carcinoma arising from the cervical epithelium. "High TGFBI expression was associated with poor OS for cervical squamous cell carcinoma and endocervical adenocarcinoma (CESC, p = 0.0024), GBM (p = 0.0082), HNSC (p = 0.013), KIRC (p = 0.0019), pancreatic adenocarcinoma (PAAD; p = 0.047), and uveal melanoma (UVM; p < 0.001)." (PMID 34671645, 2021).